ARL4D (ARF like GTPase 4D)
Description:
Small GTP-binding protein which cycles between an inactive GDP-bound and an active GTP-bound form, and the rate of cycling is regulated by guanine nucleotide exchange factors (GEF) and GTPase-activating proteins (GAP). GTP-binding protein that does not act as an allosteric activator of the cholera toxin catalytic subunit. Recruits CYTH1, CYTH2, CYTH3 and CYTH4 to the plasma membrane in GDP-bound form.
Synonyms: ARF4L
Tractability: Antibody: UniProt places it where antibodies can reach, with high confidence; its Gene Ontology location is reachable by antibodies, with high confidence. PROTAC: ubiquitination databases record sites on it.
Gene: Protein-coding gene on chromosome 17 (43,398,150 to 43,401,137, forward strand). Ensembl gene ENSG00000175906.
Subcellular location: Nucleus, nucleolus; Cell membrane; Nucleus; Cytoplasm
Subcellular location (Human Protein Atlas): Vesicles; Golgi apparatus
Gene Ontology:
Molecular function: protein binding; GTP binding; GTPase activity
Biological process: intracellular protein transport; protein secretion
Cellular component: cytoplasm; plasma membrane; nucleolus; nucleus
Genetic constraint (gnomAD): Loss-of-function variants: 1 observed, 1.72 expected, observed/expected ratio (o/e) 0.58, 90% interval 0.19 to 1.8. That is too few expected variants to judge how well the gene tolerates losing a copy. Missense variants: 230 observed, 273.32 expected, observed/expected ratio (o/e) 0.84, 90% interval 0.75 to 0.94. Synonymous variants: 102 observed, 117.58 expected, observed/expected ratio (o/e) 0.87, 90% interval 0.74 to 1.02.
Homologues: Orthologues: chimpanzee ARL4D (100% identical), macaque ARL4D (100% identical), dog ARL4D (99% identical), pig ARL4D (98% identical), rabbit ARL4D (96% identical), mouse Arl4d (95% identical), rat Arl4d (95% identical), guinea pig ARL4D (84% identical), zebrafish arl4d (76% identical). Paralogues in human: ARL4A (60% identical), ARL4C (57% identical), ARF3 (40% identical), ARF1 (39% identical), ARF5 (39% identical), ARL14 (38% identical), ARF4 (37% identical), ARF6 (36% identical), TRIM23 (35% identical), ARL11 (34% identical), ARL3 (33% identical), ARL5B (33% identical), and 18 more.
Diseases named in the same sentence as ARL4D in open-access papers:
ARL4D is named in the same sentence as 19 diseases in open-access papers, as found by Europe PMC text mining. Sharing a sentence is not in itself a finding about the gene and the disease. The quoted sentences say what the papers report.
glioma (2 papers, 2014 to 2022). A benign or malignant brain and spinal cord tumor that arises from glial cells (astrocytes, oligodendrocytes, ependymal cells). "Even though ARL4D was previously identified as a glioma-associated antigen dependent on loss of PTEN and consequent activation of Akt/mTOR pathway, its oncogenic roles and underlying molecular mechanisms have never been reported in any cancer type before." (PMID 36273157, 2022).
viral infection (2 papers, 2018 to 2022). "Arl4d-deficiency in CD8 T cells also enhanced their expansion and effector function during viral infection in vivo." (PMID 30382149, 2018). "Reversely, Arl4d-deficient CD8 T cells show enhanced IL-2 production and maturation into effector cells during viral infection in vivo." (PMID 30382149, 2018). "In CD8 T cells, Arl4d expression interferes with Akt signaling and leads to the reduced development of both cytokine (IL-2 and IFNγ)-producing CD8+ effector T cells and short-lived effector cells (SLEC) in the context of viral infection in vivo." (PMID 36078047, 2022). "More specifically, our data shown that Arl4d interferes with signal transduction via the PI3K/Akt axis, leading to inhibition of cytokine production (IL-2) and suppression of SLEC development during viral infection." (PMID 30382149, 2018). "In the absence of Arl4d, we previously showed that CD8 T cells gain effector function in the context of in vivo viral infection." (PMID 36078047, 2022). "Indeed, the lack of Arl4d results in higher IL-2 production and more pronounced effector cell development, as measured by an increase in KLRG1posCD127neg short-lived effector CD8 T cells during viral infection in vivo." (PMID 30382149, 2018).
autism (1 paper, 2022). Persistent deficits in social interaction and communication and interaction as well as a markedly restricted repertoire of activity and interest as well as repetitive patterns of behavior. "In adult mice, Arl4d is expressed in neocortical layer 1 and hippocampus, mostly in cortical interneurons (CIN), whose loss or alteration have been related to neurological disorders such as autism, schizophrenia, and epilepsy." (PMID 35836289, 2022).
colitis (1 paper, 2022). Inflammation of the colon. "To test whether CD4 T cells were similarly affected by Arl4d deficiency, we used the model of transfer colitis by the adoptive transfer of CD25negCD62Lhigh CD4 T cells from either Arl4d+/+ or Arl4d−/− mice into Rag2-deficient mice." (PMID 36078047, 2022). "As such, Arl4d−/− CD4 T cells induced significantly less colonic inflammation and lymphocytic infiltration in a model of transfer colitis." (PMID 36078047, 2022). "This increased cytokine production by Arl4d−/− CD4 T cells, however, does not exacerbate CD4 T-cell-driven colitis but rather protects from extensive tissue inflammation and cell infiltration." (PMID 36078047, 2022).
endometrial cancer (1 paper, 2022). Primary or metastatic malignant neoplasm involving the endometrium (mucous membrane that lines the endometrial cavity). "In the case of the ADP-ribosylation factor (ARF)/ARF-like protein (ARL) family, it was observed that a high expression of ARL4D, ARL1, ARF1, and SAR1B in endometrial cancer is associated with better prognosis, while a high expression of ARL4C, ARL2, ARL10, ARL16, and ARL14 promotes worse survival." (PMID 35163161, 2022).
neuroblastoma (1 paper, 2021). Neuroblastoma (NB) is the most common solid, extracranial childhood tumor. "Upregulated ARL4D promotes neurite outgrowth in N1E-115 neuroblastoma cells." (PMID 34585646, 2021).
schizophrenia (1 paper, 2022). A major psychotic disorder characterized by abnormalities in the perception or expression of reality. "Most strikingly, we found that both DMP (such as CSMD1) and DMRs (DAXX and ARL4D) are annotated to genes related to neurological disorders such as ASD, PTSD and schizophrenia, pointing out to the potential risk of these children to suffer from these disorders." (PMID 35836289, 2022).
Sepsis (1 paper, 2019). Sepsis is defined as life-threatening organ dysfunction caused by a dysregulated host response to infection. "Interestingly, several of the genes linked to glucocorticoid signaling (Arl4d, Cdkn1a, Ddit4, Fkbp5, Gjb6, Il6ra, Klf15, Nfkbia, Rhob, Sdc4, Sgk1, Sult1a1, Tob2, Wipf3) and apoptotic process were still upregulated 4 days post-sepsis." (PMID 31278440, 2019).
cancer (2 papers, 2022 to 2024). A tumor composed of atypical neoplastic, often pleomorphic cells that invade other tissues. "ARL family proteins including ARL4D, are involved in cancer cell migration, invasion, and proliferation." (PMID 38172584, 2024). "Accordingly, ARL4D, a member of the newly identified SE-driven core transcriptional regulatory network of G3-MB with very little prior knowledge in cancer, was subjected to further investigation." (PMID 36273157, 2022).
tumor (2 papers, 2022 to 2024). "To dissect the molecular mechanism underlying ARL4D’s tumor-dependency of G3-MB, we performed RNA-seq analysis of MB002 cells stably expressing two separate shARL4D clones or scramble control shRNA." (PMID 36273157, 2022). "ARL4D loss induced growth inhibition of G3-MB cells resulted from disruption of proliferation and induction of apoptosis of tumor cells." (PMID 36273157, 2022). "Furthermore, we showed loss of ARL4D caused cell cycle arrest at G2/M phase and significantly attenuated tumor-sphere formation in both D425 and MB002 lines." (PMID 36273157, 2022). "Collectively, our results demonstrated that ARL4D, which is required for maintaining cell cycle progression and inhibiting neural differentiation of tumor cells, represents a novel SE-associated subtype-specific tumor-dependency and therapeutic target of G3-MB." (PMID 36273157, 2022). "Single-cell transcriptomic analysis also showed that G3-MB tumor cells exhibited much stronger ARL4D expression than tumor cells of the other three MB subtypes." (PMID 36273157, 2022). "ARL4D represents a G3/G4-MB SE at tumor tissue level and exhibits robustly elevated H3K27Ac signals in G3-MB lines versus UW228." (PMID 36273157, 2022). "Like GP3-C2, GP4-C2, the photoreceptor differentiated tumor cell cluster of G4-MB, exhibits the highest expression of ARL4D and highly expresses OTX2 and CRX." (PMID 36273157, 2022). "We then compared the expression and tumor-dependency of ARL4D in D425 and MB002 versus UW228." (PMID 36273157, 2022). "Taken together, our results verified ARL4D as a subtype-specific tumor-dependency of G3-MB." (PMID 36273157, 2022). "Moreover, GP3-C2, the photoreceptor differentiated tumor cell cluster of G3-MB, exhibits the highest expression of ARL4D among all the identified tumor cell clusters." (PMID 36273157, 2022). "Therefore, it would be interesting to test in future whether ARL4D also works as an essential gene and is transcriptionally regulated by OTX2 and CRX as well in ARL4D-high G4-MB tumors if proper tumor models are available." (PMID 36273157, 2022). "The analysis revealed most cells in tumor microenvironment including stromal cell expressed EGFR, NFE2, and FSL1 genes while a lower number of cells expressed CDH3, ARL4D, and SH3RF2." (PMID 38172584, 2024). "Moreover, our scRNA-seq data analysis also revealed ARL4D, OTX2 and CRX were all enriched in GP3-C2, the photoreceptor differentiated tumor cell cluster of G3-MB defined in a recent single-cell transcriptomic study of MB." (PMID 36273157, 2022). "In addition, ARL4D, SH3RF2, and FOSL1 were found to be expressed in tumor immune cells (TICs)." (PMID 38172584, 2024).
infection (1 paper, 2018). The state of being infected such as from the introduction of a foreign agent such as serum, vaccine, antigenic substance or organism. "Moreover, also in the spleen and the infection site liver, development of Arl4d−/− T cells into KLRG1+CD127− SLEC was more pronounced, similar to the observation in the blood." (PMID 30382149, 2018).
ARL4D also shares sentences with these, for which no sentence is quoted: adenovirus infection (1 paper); bladder cancer (1); breast carcinoma (1); epilepsy (1); Intellectual disability (1); neurological disorders (1); osteoporosis (1); retinal disease (1).